KLHL23 (kelch like family member 23)
Synonyms: MGC2610; FLJ37812; MGC22679; PHOSPHO2-KLHL23; DITHP
Tractability: Small molecule: it belongs to a druggable protein family. PROTAC: ubiquitination databases record sites on it.
Gene: Protein-coding gene on chromosome 2 (169,694,488 to 169,776,989, forward strand). Ensembl gene ENSG00000213160.
Subcellular location (Human Protein Atlas): Actin filaments; Nucleoplasm
Gene Ontology:
Molecular function: protein binding; ubiquitin-like ligase-substrate adaptor activity
Biological process: proteasome-mediated ubiquitin-dependent protein catabolic process
Cellular component: Cul3-RING ubiquitin ligase complex; cytoplasm
Genetic constraint (gnomAD): Loss-of-function variants: 33 observed, 49.07 expected, observed/expected ratio (o/e) 0.67, 90% interval 0.51 to 0.9. The upper end of that interval is the gene's LOEUF score, 0.9, which puts it in group 3 of 6, group 1 being the genes least tolerant of losing a copy. Missense variants: 589 observed, 685.72 expected, observed/expected ratio (o/e) 0.86, 90% interval 0.8 to 0.92. Synonymous variants: 224 observed, 236.23 expected, observed/expected ratio (o/e) 0.95, 90% interval 0.85 to 1.06.
Homologues: Orthologues: chimpanzee KLHL23 (99% identical), macaque KLHL23 (99% identical), dog KLHL23 (99% identical), pig KLHL23 (98% identical), guinea pig KLHL23 (97% identical), mouse Klhl23 (97% identical), rat Klhl23 (97% identical), rabbit KLHL23 (96% identical), tropical clawed frog klhl23 (71% identical), zebrafish klhl23 (61% identical). Paralogues in human: KLHL29 (30% identical), KLHL28 (30% identical), KLHL12 (30% identical), KLHL18 (30% identical), KLHL17 (29% identical), KLHL20 (29% identical), KLHL3 (29% identical), KLHL2 (28% identical), KLHL21 (28% identical), IPP (28% identical), KLHL24 (28% identical), KLHL4 (28% identical), and 42 more.
Diseases named in the same sentence as KLHL23 in open-access papers:
KLHL23 is named in the same sentence as 20 diseases in open-access papers, as found by Europe PMC text mining. Sharing a sentence is not in itself a finding about the gene and the disease. The quoted sentences say what the papers report.
gastric cancer (3 papers, 2016 to 2022). A primary or metastatic malignant neoplasm involving the stomach. "A recent study found that overexpression of KLHL23 protein from read-through transcription of PHOSPHO2-KLHL23 increased cell proliferation in gastric cancer cells." (PMID 35833210, 2022). "The expression of KLHL23 from prevalent read‐through transcripts of PHOSPHO2‐KLHL23 in gastric cancer may undermine the efficacy of anticancer drug treatment." (PMID 27833855, 2016).
hepatocellular carcinoma (2 papers, 2022 to 2024). A malignant tumor that arises from hepatocytes. "Notably, KLHL23 levels correlated with survival in cancers such as hepatocellular carcinoma and low-grade glioma." (PMID 39636292, 2024).
bladder urothelial carcinoma (1 paper, 2024). "Conversely, lower levels of KLHL23 expression were observed in five types of cancer when compared to normal tissue: bladder urothelial carcinoma (BLCA), ovarian cancer (OV), testicular germ cell tumors (TGCT), thyroid carcinoma (THCA), and uterine corpus endometrial carcinoma (UCEC)." (PMID 39636292, 2024).
cone-rod dystrophies (1 paper, 2018). "In addition to this, we also detected differentially expressed genes directly ascribed to retinal diseases such as Klhl23 or Nr2e3 involved in cone-rod dystrophies or RP, respectively." (PMID 29847644, 2018).
liver cancer (1 paper, 2024). An epithelial or non-epithelial malignant neoplasm that arises from the liver. "Liver cancer samples with mutation in KLHL23 showed higher cancer stage, and those patients had a worse prognosis." (PMID 39636292, 2024). "Our results showed that high expression of KLHL23 was associated with a poor prognosis in patients with liver cancer (LIHC, P = 0.002), adrenocortical carcinoma (ACC, P = 0.003), Kidney renal papillary cell carcinoma (KIRP, P = 0.006), and skin cutaneous melanoma (SKCM, P = 0.025)." (PMID 39636292, 2024). "KLHL23 suppresses the EMT in liver cancer cells by obstructing their ability to reorganize the actin cytoskeleton." (PMID 39636292, 2024).
stomach tumor (1 paper, 2016). "Of note, PHOSPHO2‐KLHL23 was the most significantly upregulated transcript in stomach tumor tissues and our investigation revealed that the KLHL23 protein is related to the tumorigenic effect." (PMID 27833855, 2016).
uveal melanoma (1 paper, 2024). A melanoma derived from melanocytes of the uveal tract. "In terms of PFI, high expression of KLHL23 was identified as a risk factor for KIRP (P < 0.001), LIHC (P < 0.001), ACC (P = 0.001), SKCM (P = 0.003), and uveal melanoma (UVM, P = 0.013), while lower expression of KLHL23 was found to be a risk factor for LGG and GBM." (PMID 39636292, 2024).
tumor (4 papers, 2016 to 2024). "By multi-omics analysis upon the transcriptomic, genomic, and methylation data, the current study explored the association of KLHL23 with patient survival, gene ontology, tumor-infiltrating lymphocytes, and drug responses." (PMID 39636292, 2024). "Our results suggest that higher levels of KLHL23 expression were linked to reduced immune and stromal cell infiltration within the tumor." (PMID 39636292, 2024). "Furthermore, this association highlights the potential role of KLHL23 in modulating the tumor microenvironment and could provide insights into the mechanisms underlying tumor progression and metastasis." (PMID 39636292, 2024). "The exact mechanisms by which KLHL23 influences tumor progression require further investigation, particularly in the context of different cancer types." (PMID 39636292, 2024). "Conversely, higher KLHL23 expression was negatively correlated with tumor-infiltrating lymphocytes (TILs), including monocytes, activated natural killer (NK) cells, and M2 macrophages." (PMID 39636292, 2024). "The observed negative correlation between KLHL23 expression and immune/stromal cell infiltration scores highlights the possible involvement of KLHL23 in regulating the tumor microenvironment." (PMID 39636292, 2024). "Comprehensive study of KLHL23 within the context of different cancer types can provide insights into its relation to tumor development and progression and potentially reveal novel therapeutic targets." (PMID 39636292, 2024). "Furthermore, signaling pathways and the characteristics of the tumor microenvironment are also critical in modulating KLHL23 expression." (PMID 39636292, 2024). "In addition, a drug sensitivity analysis of KLHL23 was used to predict more personalized treatment strategies by assessing individual tumor responses to specific drugs." (PMID 39636292, 2024). "While, the regulation effect of KLHL23 across human cancers remains largely unknown, and its role in tumor microenvironment needs further studies." (PMID 39636292, 2024). "Among these genes, PHOSPHO2, KLHL23, TRIM39, TSNAX-DISC1 and RPP21 expression were significantly elevated in the tumor tissues compared with the non-tumor tissues of HCC according to TCGA database." (PMID 35833210, 2022). "Comparing the effects of KLHL23 expression on immune pathways, we observed that both type II IFN response and cytolytic activity were decreased in the high KLHL23 expression group, indicating that KLHL23 affects the anti-tumor activity of the tumor immune microenvironment." (PMID 39636292, 2024). "Moreover, tumor mutational burden (TMB) and microsatellite instability (MSI) show negative correlation with KLHL23 expression levels in COAD, KIRC, and KIRP." (PMID 39636292, 2024). "This study found that several genes including PHOSPHO2, KLHL23, TSNAX-DISC1, TRIM39 and RPP21 were upregulated by SOF and the expression levels of these genes were higher in tumor than in non-tumor parts of patients with HCC according to the TCGA database." (PMID 35833210, 2022).
cancer (2 papers, 2022 to 2024). A tumor composed of atypical neoplastic, often pleomorphic cells that invade other tissues. "The study also highlighted how reduced KLHL23 expression is linked to increased immune activity and sensitivity to chemotherapy, suggesting its potential as a biomarker for cancer prognosis and treatment responsiveness." (PMID 39636292, 2024). "Our research expands upon this foundation by examining KLHL23 across multiple dimensions, including methylation status, mutations, clinical outcomes, and immune cell infiltration in a wide range of cancers." (PMID 39636292, 2024). "The differential expression analysis of KLHL23 may prove beneficial in the development of diagnostic tools for the early detection of cancer." (PMID 39636292, 2024). "Our findings indicated that KLHL23 expression levels were elevated in advanced stages of several cancers, including LIHC, LUAD, KIRC, and ESCA." (PMID 39636292, 2024). "In conclusion, our research not only confirms previous studies, but also provides new insights into the diverse functions of KLHL23 in cancer." (PMID 39636292, 2024). "Further analysis was conducted to examine the prognostic significance of KLHL23 expression in various cancer types." (PMID 39636292, 2024). "The precise functions of KLHL23 remain to be elucidated, yet its potential role in cancer biology is a subject of ongoing investigation." (PMID 39636292, 2024). "Previous studies have suggested the potential involvement of KLHL23 in cancer development, with some focusing on specific aspects such as genetic mutations or expression levels." (PMID 39636292, 2024). "In discussing our findings, while we have uncovered crucial aspects of KLHL23’s involvement in cancer, many questions remain unanswered." (PMID 39636292, 2024). "We also examined various factors, including gene expression, survival status, DNA methylation, genetic alterations, immune infiltration, and relevant cellular pathways, to elucidate the possible molecular mechanisms of KLHL23 in human cancers." (PMID 39636292, 2024). "KLHL23 expression levels in various cancers are influenced by a variety of factors, including genetic alterations such as copy number variations and mutations." (PMID 39636292, 2024). "Overall, the findings of our study shed new light on the diverse functions of KLHL23 across a spectrum of cancers, paving the way for future research and potential clinical applications." (PMID 39636292, 2024). "This research provides deep insight into the role of KLHL23 in the progression of various cancers." (PMID 39636292, 2024). "High KLHL23 expression was found to be a risk factor for OS, DSS, and PFI in many cancer types." (PMID 39636292, 2024). "Subsequently, we employed Gene Set Cancer Analysis (GSCA) to scrutinize whether a copy number variation (CNV) and DNA methylation in KLHL23 influenced its expression across 33 different cancer types." (PMID 39636292, 2024). "Additionally, epigenetic modifications are known to affect KLHL23 expression in different cancer types." (PMID 39636292, 2024). "GO enrichment pathways in the KLHL23 high expression group across cancers were similar and could be classified into three categories: immune response and T cell activation pathways, extracellular matrix adhesion pathways, and RNA splicing and ion transport pathways." (PMID 39636292, 2024). "Additionally, we investigated the relationship between KLHL23 expression and cancer stage." (PMID 39636292, 2024). "We analyzed the expression of KLHL23 in different tumors, examined how its expression correlated with patient’s outcomes and overall survival rates, and investigated how its genetic or epigenetic alterations might contribute to cancer development." (PMID 39636292, 2024). "In this paper, the cancerous role of Kelch-like family member 23 (KLHL23) was comprehensively analyzed with TCGA and single cell GEO database across overall 33 cancer types." (PMID 39636292, 2024).
cancer (continued). "Single-variate Cox regression analysis was performed to examine the relationship between KLHL23 expression levels and OS, DFI, DSS, and PFI in different cancer types." (PMID 39636292, 2024). "In specific cancer contexts, such as LIHC, KLHL23 expression exhibited a negative association with the IL6-JAK-STAT3 signaling pathway, but a positive association with the G2M checkpoint and MYC gene targeting signaling pathway." (PMID 39636292, 2024).
KLHL23 also shares sentences with these, for which no sentence is quoted: Bardet-Biedl syndrome (1 paper); Chorioretinal atrophy (1); glioma (1); ovarian carcinoma (1); retinal diseases (1); retinoschisis (1); skin cutaneous melanoma (1); stomach adenocarcinoma (1); testicular germ cell tumor (1); thyroid carcinoma (1); uterine corpus endometrial carcinoma (1).